BCL2 (BCL2 apoptosis regulator)
Diseases named in the same sentence as BCL2 in open-access papers (continued):
Sharing a sentence is not in itself a finding about the gene and the disease.
chronic lymphocytic leukemia (continued). "This compound inhibits Bcl-2 protein synthesis by inactivating Bcl-2 mRNA and has shown chemosensitizing effects in combination with other conventional chemotherapeutic drugs, especially in chronic lymphocytic leukemia patients." (PMID 24212653, 2011). "Previous studies on B cells of chronic lymphocytic leukemia showed that the mitochondria-dependent Bcl-2 signaling pathway of apoptosis plays a critical role in the killing of targeted cancer cells by immunotoxins." (PMID 21305058, 2011). "For instance, members of the let-7 miRNA family can negatively regulate all three members of the RAS oncogene family, and miR-15a/miR-16-1 can target and regulate BCL2 in B-cell CLL cells." (PMID 20102618, 2010). "For example, miR15a is a suppressor for Bcl-2 in chronic lymphocytic leukemia (CLL), prostate cancer, and myeloma." (PMID 24281040, 2010). "The recent development and clinical success of the BCL-2 inhibitor venetoclax (ABT-199) as treatment for chronic lymphocytic leukemia, acute myeloid leukemia and other hematologic malignancies has shown that targeting apoptosis directly has the potential to significantly improve patient outcomes." (PMID 41507122, 2026). "Bcl-2 plays a pivotal role in hematological malignancies with its overexpression driving leukemic cell survival, a key mechanism in the pathogenesis of diseases like chronic lymphocytic leukemia (CLL)." (PMID 40841912, 2025). "The integration of BTK and BCL2 inhibitors into the treatment of patients with chronic lymphocytic leukemia (CLL) represents a paradigm shift and has led to significant improvements in clinical outcomes, including prolonged survival and enhanced quality of life." (PMID 40555733, 2025). "Such conclusions were drawn 20 years ago, where a relationship was indicated between the reduced expression of miR-15 and miR-16 in B cells and the increase in the level of Bcl-2 protein together with inhibition of apoptosis of cancer cells in chronic lymphocytic leukemia (CLL)." (PMID 38473390, 2024). "The BCL2 inhibitor, Venetoclax, induces apoptosis and could potentially be used to treat various cancers, such as chronic lymphocytic leukemia." (PMID 38361755, 2024). "Moreover, BAX-mutated CH has been shown to arise after the treatment with a BCL-2 inhibitor, venetoclax, in patients with chronic lymphocytic leukemia (CLL), strongly reflecting the evolutionary dynamics in response to targeting antiapoptotic proteins." (PMID 39352380, 2024). "For example, rs539846 located in a SE affects chronic lymphocytic leukemia susceptibility through differential binding to RELA (NF-kappa-B subunit) and direct modulation of BMF expression, impacting the antiapoptotic protein B cell lymphoma 2 (BCL2)." (PMID 38410974, 2024). "Considering the fact that patients with chronic lymphocytic leukemia (CLL) that is sensitive to VEN are dependent on high BCL‐2 expression in CLL cells, VEN may be sensitive to MLL‐rearranged AML." (PMID 36819153, 2023). "The B cell leukemia/lymphoma 2 (BCL-2) inhibitor venetoclax is effective in chronic lymphocytic leukemia (CLL); however, resistance may develop over time." (PMID 37751299, 2023). "High levels of BCL-2 were also detected in several other haematological malignancies, including chronic lymphocytic leukemia (CLL), diffuse large B cell lymphoma (DLBCL) and mantle cell lymphoma and in certain solid tumours, including subsets of brain, breast and lung cancer." (PMID 36342579, 2023). "The only currently approved BH3-mimetic, the selective BCL2 inhibitor venetoclax, is highly efficacious in chronic lymphocytic leukemia and has rapidly advanced to an approved standard of care in frontline and relapsed disease in combination with anti-CD20 monoclonal antibodies." (PMID 35659041, 2022).
chronic lymphocytic leukemia (continued). "Bcl-2-specific inhibitors, such as venetoclax, have recently been approved for the treatment of chronic lymphocytic leukemia and small lymphocytic lymphoma, and they are showing promise in clinical trials as a targeted therapy for patients with relapsed or refractory acute myeloid leukemia (AML)." (PMID 36099249, 2022). "Downregulation of miR-16 has been long known to be a main event in CLL (chronic lymphocytic leukemia), but its upregulation seems to play a pivotal role in regulating BCL2 (by binding the 3′-UTR region of BCL2) and in mediating prednisolone-induced apoptosis in childhood T-ALL." (PMID 36010971, 2022). "The main regulators of apoptosis include both the pro-survival and pro-apoptotic proteins of the Bcl-2 (B-cell CLL/lymphoma 2) family such as Bcl-2 (B-cell lymphoma 2), Bcl-x (BCL2 like 1) with Bcl-xL (B-cell lymphoma extra-large) and Bax (Bcl-2-associated X protein) as well as the caspases." (PMID 35409218, 2022). "Chronic lymphocytic leukemia cells can effectively evade apoptosis due to their marked dependence on BCL-2 activity; in other malignancies, distinct members of the BCL-2 family by contrast may have a greater influence." (PMID 36071980, 2022). "The BCL2 inhibitor ABT-199 has been used to treat chronic lymphocytic leukemia and AML." (PMID 36145287, 2022). "While resulting in impressive improvement in objective outcomes, particularly for patients with chronic lymphocytic leukemia/small lymphocytic lymphoma and acute myeloid leukemia, the use of venetoclax has exposed a variety of resistance mechanisms to BCL-2 inhibition." (PMID 34198580, 2021). "For a long time, the simplistic view of an apoptosis defect predominant in lymphoid proliferations (chronic lymphocytic leukemia [CLL] type) and an increase in proliferation as the hallmark of AMLs has prevailed, with the known successes in the use of the BCL-2 inhibitor venetoclax in CLL." (PMID 34176517, 2021). "The success of the BCL-2 inhibitor Venetoclax, in patients with chronic lymphocytic leukemia, small lymphocytic lymphoma, and as a combinatorial therapy in acute myeloid leukemia, clearly demonstrates that the protein–protein interactions of BCL-2 family proteins are druggable." (PMID 33162554, 2021). "In addition, apoptosis in chronic lymphocytic leukaemia (CLL) cells was prevented through Bcl-2-dependent pathways as a response to IL-4, INFα and bFGF factors." (PMID 34829672, 2021). "Our results showed that the known VEN resistance-associated BCL2 mutation was not present in our cohort, indicating that, in contrast to chronic lymphocytic leukemia, this BCL2 mutation is dispensable for acquired VEN resistance in AML." (PMID 33933163, 2021). "The Bruton’s tyrosine kinase (BTK) inhibitors, along with other targeted drugs such as the BCL-2 inhibitors, have fundamentally changed the treatment landscape of chronic lymphocytic leukemia (CLL) and have been transforming the treatment algorithms of other B cell malignancies." (PMID 34485307, 2021). "Hence, inhibitors specific for Bcl‐2 or Mcl‐1 have been developed as direct inducers for tumor cell apoptosis in chronic lymphocytic leukemia and small lymphocytic lymphoma, and hamper tumor progression both in patients and in tumor mouse models." (PMID 34766113, 2020). "Ibrutinib-Navitoclax was ranked as the third-best combination for further study; such combinations (Ibrutinib with Bcl2 inhibitors) have shown promising results in phase II clinic trial (NCT02756897) for chronic lymphocytic leukemia (CLL), and recently suggested as the first-line treatment for CLL." (PMID 32012154, 2020). "Other Bcl-2 inhibitory agents that have been studied in cancer clinical trials include obatoclax mesylate, an indole-based Bcl-2 inhibitor that received orphan drug designation in the US, in 2004, for the treatment of chronic lymphocytic leukemia." (PMID 33256166, 2020).
chronic lymphocytic leukemia (continued). "Accordingly, the approval of venetoclax (ABT-199), a small molecule BCL-2 inhibitor, in patients with chronic lymphocytic leukemia and acute myeloid leukemia has become the proverbial torchbearer for novel candidate drug approaches selectively targeting the BCL-2 superfamily." (PMID 32131385, 2020). "SNP rs2168101 resides in SE of the first intron of LIM domain only 1 (LMO1), and SNP rs539846 locates in the intron 3 of B cell lymphoma 2 (BCL2)-modifying factor (BMF) SE, both of them influence neuroblastoma and chronic lymphocytic leukemia (CLL) susceptibility, respectively." (PMID 32278350, 2020). "Moreover, miR-15/-16 regulate cell death by targeting BCL2, which is an important mechanism in chronic lymphocytic leukemia." (PMID 30474694, 2019). "Similarly, in lymphoma, let-7a alongside with other miRNAs are upregulated by Romidepsin, decreasing anti-apoptotic proteins such as BCL-2 (B-cell CLL/lymphoma 2) and BCL-XL (BCL2-like 1)." (PMID 31658720, 2019). "Overexpression of BCL2 is also frequently observed in B cell chronic lymphocytic leukemia (CLL)." (PMID 29985390, 2018). "Venetoclax specifically targeting BCL-2 has been approved for treatment of chronic lymphocytic leukemia, and several other BH3 mimetics, such as navitoclax targeting BCL-2, BCL-xL, and BCL-w, are currently under clinical trials for several hematological malignancies." (PMID 29928488, 2018). "Subsequent rational drug discovery research efforts led to the development of VenclextaTM (ABT-199), the first orally active BCL-2 selective (BCL-XL-sparing) inhibitor that has been recently approved in high risk patients with relapsed or refractory Chronic Lymphocytic Leukemia (CLL)." (PMID 29732004, 2018). "The first study of altered miRNA expression in cancer showed that miR-15 and miR-16, targeting the anti-apoptotic factor B cell lymphoma 2 (BCL2), are located at a chromosomal region (13q14), frequently deleted in the majority of chronic lymphocytic leukemia (CLL) cases." (PMID 29419779, 2018). "One prime example of how cell death pathways can be targeted for therapeutic purposes is the development of the BCL-2 inhibitor ABT-199 that has recently received breakthrough status by the Federal Drug Administration for the treatment in chronic lymphocytic leukemia and acute myeloid leukemia." (PMID 29371590, 2018). "Similarly, miR-15a and miR-16-1, found deleted or down-regulated in the majority of chronic lymphocytic leukemias (CLLs), can directly negatively regulate BCL-2 in CLL." (PMID 29018797, 2017). "Furthermore, treatment of chronic lymphocytic leukemia cells led to a reduction in the Bcl-2/Bax ratio." (PMID 28542253, 2017). "Bcl2 is uniformly expressed in chronic lymphocytic leukemia and promotes leukemia cell survival." (PMID 28256505, 2017). "For example, the small molecule ABT-737 (and related ABT-263) targeting Bcl-2, Bcl-xL and Bcl-w exhibits dose-limiting thrombocytopenia in treating Bcl-2-dependent chronic lymphocytic leukemia due to excessive inhibition of Bcl-xL, which has a role in platelet development." (PMID 27805565, 2016). "Similarly, activation of serine/threonine-protein kinases (Akt2 and Akt3) in combination with B-cell CLL/lymphoma (Bcl2), collagen (COL4A1), Src transforming protein (SHC1) lead to the activation of focal adhesion pathway." (PMID 27367858, 2016). "AUF1 may be involved in the stabilization of Bcl2 mRNA, but we cannot exclude roles for other RBPs, like nucleolin, which may contribute to this effect in chronic lymphocytic leukemia cells." (PMID 25680182, 2015). "Thus it has been shown that both UCN-01 and flavopiridol decrease the expression of Mcl-1, XIAP, BAG-1, and Bcl-2 in B-cell chronic lymphocytic leukemia cells." (PMID 23527225, 2013). "In addition, the anti-apoptotic protein Bcl-2 is a target of miR-15a in chronic lymphocytic leukemia (CLL), where restoration of miR-15a induces apoptosis in MEG-01 cell line, suggesting a tumor suppressor function of miR-15a." (PMID 22629365, 2012).
chronic lymphocytic leukemia (continued). "The advent of venetoclax, a selective Bcl-2 inhibitor, has reshaped the treatment landscape for cancers like chronic lymphocytic leukemia (CLL) and other lymphoid malignancies." (PMID 40841912, 2025). "Targeted therapies using BTK inhibitors (BTKi) and/or BCL2 inhibitors (BCL2i) represent a paradigm shift in the management of patients with chronic lymphocytic leukemia (CLL) and have led to significant improvements in patient outcomes." (PMID 40555733, 2025). "Venetoclax/ABT199 (VEN) is a Bcl-2-specific inhibitor, clinically approved for the treatment of chronic lymphocytic leukemia (CLL) and acute myeloid leukemia (AML)." (PMID 40707672, 2025). "Reduced BMF-SE activity in chronic lymphocytic leukaemia (CLL) due to carrying the rs539846 risk allele (A) at the RELA binding site leads to the disruption of RELA binding, decreased BMF expression, and, therefore, BMF’s inability to inhibit the antiapoptotic protein BCL2." (PMID 38542080, 2024). "Notably, belinostat, an inhibitor of histone deacetylase (HDAC), was sanctioned for the treatment of T-cell lymphoma, while ABT-199, a highly selective inhibitor of Bcl-2, was approved for patients with chronic lymphocytic leukemia (CLL) exhibiting a 17p chromosomal deletion." (PMID 38399404, 2024). "The oral, highly selective Bcl2 inhibitor venetoclax has substantially improved the therapeutic landscape of chronic lymphocytic leukemia (CLL)." (PMID 36982875, 2023). "The incorporation of the B cell leukemia/lymphoma 2 (BCL-2) inhibitor venetoclax into the treatment paradigm for chronic lymphocytic leukemia (CLL) and acute myeloid leukemia (AML) has revolutionized the treatment of these diseases." (PMID 37751299, 2023). "Venetoclax (VEN) is a potent oral inhibitor of the anti-apoptotic molecule BCL2, approved for adults with chronic lymphocytic leukemia (CLL), and recently for naïve acute myeloid leukemia (AML) unfit for intensive chemotherapy." (PMID 35008186, 2021). "The approval of Bruton’s tyrosine kinase (BTK) inhibitors such as ibrutinib and acalabrutinib and the Bcl-2 inhibitor venetoclax have revolutionized the treatment of chronic lymphocytic leukemia (CLL)." (PMID 33809580, 2021). "Venetoclax (ABT-199) is a Bcl-2 inhibitor currently approved for the treatment of chronic lymphocytic leukemia (CLL) and acute myeloid leukemia (AML) in adult patients ineligible for intensive chemotherapy." (PMID 34381700, 2021). "Overexpression of BCL2 in chronic lymphocytic leukemia (CLL) and acute lymphocytic leukemia (ALL) cells renders these cancer cells resistant to chemotherapy." (PMID 32650615, 2020). "miRNA dysregulation in cancer was first reported in 2002, when miR-15 and miR-16 were identified at 13q14.3, a frequently deleted region in chronic lymphocytic leukemia (CLL), leading to the overexpression of their target, i.e., BCL-2 (B cell lymphoma 2)." (PMID 31658720, 2019). "In addition, high expression levels of Bcl‐2 are observed in B‐cell chronic lymphocyte leukemia and in neoplastic cells showing defective programmed cell death 8, 9, collectively indicating that Bcl‐2 expression is crucial for development and growth of various types of tumors." (PMID 30524947, 2018). "Furthermore, results from phase III trials of oblimerson (Genasense), an antisense nucleotide that targets Bcl-2, in chronic lymphocytic leukaemia showed improved survival rates only when given in conjunction with conventional chemotherapy but not when used alone." (PMID 21063399, 2010). "The treatment of chronic lymphocytic leukemia (CLL) has significantly shifted from chemoimmunotherapy to targeted therapies like Bruton's tyrosine kinase and BCL2 inhibitors." (PMID 42123307, 2026).
chronic lymphocytic leukemia (continued). "Therapy for chronic lymphocytic leukemia (CLL) has evolved dramatically with the introduction of targeted agents, particularly Bruton tyrosine kinase inhibitors (BTKis) and BCL2 inhibitors (BCL2is)." (PMID 42278639, 2026). "A potent Bcl-2 inhibitor, venetoclax, has been approved by the FDA to treat patients with 17p deletions in chronic lymphocytic leukemia (CLL)." (PMID 40400713, 2025). "Similar to this, malignant cells in chronic lymphocytic leukemia (CLL) have an anti-apoptotic phenotype that is typified by lower Bax levels and high Bcl-2 levels." (PMID 40868135, 2025). "Venetoclax (ABT-199), a BCL-2-specific inhibitor, has achieved clinical approval for treating BCL-2-dependent hematological malignancies, such as small lymphocytic lymphoma and chronic lymphocytic leukemia." (PMID 40699886, 2025). "Resistance to the Bcl-2-specific inhibitor, Venetoclax (VEN), poses a therapeutic challenge in the management of chronic lymphocytic leukemia and acute myeloid leukemia." (PMID 40707672, 2025). "The BCL2 inhibitor venetoclax (VEN) has been successfully utilized in the treatment of various hematological malignancies, particularly chronic lymphocytic leukemia (CLL) and acute myeloid leukemia (AML)." (PMID 41394964, 2025). "Common medications used to treat newly diagnosed and relapsed/refractory chronic lymphocytic leukemia (CLL) include Bruton tyrosine kinase inhibitors (BTKi) and B-cell lymphoma-2 inhibitors (BCL-2)." (PMID 39858050, 2025). "Some small molecule inhibitors of BCL2 family were also reported as entering clinical trials, such as ABT-263/navitoclax, or approved for the treatment of chronic lymphocytic leukemia like ABT-199/venetoclax, due to its BCL2 specificity and low toxicity." (PMID 40064873, 2025). "Recently, the single target BCL-2 inhibitor venetoclax, which was approved by the FDA for acute myeloid leukemia and chronic lymphocytic leukemia, showed therapeutic effect on multiple PDXs of SCLC." (PMID 38961535, 2024). "The first one to be granted an authorization for the treatment of adult patients with CLL or small lymphocytic lymphoma (SLL) who have received at least two lines of therapy, including a BTK and a BCL-2 inhibitor, was pirtobrutinib." (PMID 38338868, 2024). "In chronic lymphocytic leukemia (CLL), interferon-α (INF-α) and basic fibroblast growth factor (bFGF) prevent tumor cell apoptosis through a Bcl-2-dependent pathway." (PMID 38672455, 2024). "The malignancies that were firstassociated with Bcl-2 overexpression were Chronic Lymphocytic Leukemia (CLL) and B-cell Lymphoma, hence the name Bcl-2 (B-cell leukemia/lymphoma-2 protein)." (PMID 36639602, 2023). "For instance, MI-2 significantly decreased anti-apoptotic proteins such as BCL2 and MCL-1 (myeloid leukemia 1) and activated the intrinsic apoptosis pathway in chronic lymphocytic leukemia." (PMID 38097554, 2023). "The most clinically advanced BH3-mimetic drug is the BCL-2-specific inhibitor venetoclax, which is approved by the FDA and many other international regulatory authorities for therapy of chronic lymphocytic leukemia (CLL) and acute myeloid leukemia (AML)." (PMID 36755070, 2023). "Chronic lymphocytic leukemia (CLL) is effectively treated with targeted therapies including Bruton tyrosine kinase inhibitors and BCL2 antagonists." (PMID 36376377, 2023). "Despite the high clinical efficacy of the specific BCL-2 inhibitor venetoclax in acute myeloid leukemia (AML) and chronic lymphocytic leukemia (CLL), dose limitation and resistance argue for the early exploration of rational combination strategies." (PMID 36674872, 2023). "Chronic lymphocytic leukemia (CLL) is an example of how targeted therapies, such as BTK, PI3K, or Bcl-2 inhibitors as well as anti-CD20 antibodies, have improved patients’ management, even when adopted as frontline treatment." (PMID 35294723, 2022).